TTK (TTK protein kinase)
Description:
Involved in mitotic spindle assembly checkpoint signaling, a process that delays anaphase until chromosomes are bioriented on the spindle, and in the repair of incorrect mitotic kinetochore-spindle microtubule attachments. Phosphorylates MAD1L1 to promote the mitotic spindle assembly checkpoint. Phosphorylates CDCA8/Borealin leading to enhanced AURKB activity at the kinetochore. Phosphorylates SKA3 at 'Ser-34' leading to dissociation of the SKA complex from microtubules and destabilization of microtubule-kinetochore attachments. Phosphorylates KNL1, KNTC1 and autophosphorylates. Phosphorylates MCRS1 which enhances recruitment of KIF2A to the minus end of spindle microtubules and promotes chromosome alignment.
Synonyms: PYT; MPS1; MPS1L1; CT96; MPH1; ESK
Tractability: Small molecule: a drug acting on it is in phase 2 or 3 trials; a structure with a bound ligand is known; a high-quality ligand is known; it has a high-quality binding pocket; it belongs to a druggable protein family. PROTAC: it is named in the literature on targeted protein degradation; ubiquitination databases record sites on it; a small molecule that binds it is known.
Target class: Kinase; Protein Kinase; Enzyme; Other protein kinase group; Other protein kinase TTK family
Chemical probes: AZ 3146, BAY1217389 (high quality), CCT251455 (high quality), CHEMBL3109933, CHEMBL3410084, MPI-0479605, MPS1-IN-1 (high quality), Mps1-IN-2 (high quality), NMS-P715 (high quality), PD080698, PD080710, PD080831, PD080863, PD081061, PD081183, PD081221, PD081349, PD081436, PD081462, PD081662, and 40 more
Gene: Protein-coding gene on chromosome 6 (80,003,887 to 80,043,580, forward strand). Ensembl gene ENSG00000112742.
Subcellular location (Human Protein Atlas): Cytosol; Nucleoli
Gene Ontology:
Molecular function: protein binding; protein serine kinase activity; protein serine/threonine kinase activity; protein serine/threonine/tyrosine kinase activity; protein tyrosine kinase activity; ATP binding; identical protein binding; kinetochore binding; protein kinase activity
Biological process: mitotic spindle assembly checkpoint signaling; repair of mitotic kinetochore microtubule attachment defect; chromosome segregation; meiotic spindle assembly checkpoint signaling; mitotic spindle organization; positive regulation of cell population proliferation; positive regulation of SMAD protein signal transduction; protein localization to kinetochore; spindle organization; negative regulation of chromosome separation; negative regulation of metaphase/anaphase transition of cell cycle; nuclear chromosome segregation; nuclear division
Cellular component: cytoplasm; membrane; kinetochore; spindle
Genetic constraint (gnomAD): Loss-of-function variants: 51 observed, 96.67 expected, observed/expected ratio (o/e) 0.53, 90% interval 0.42 to 0.67. The upper end of that interval is the gene's LOEUF score, 0.67, which puts it in group 2 of 6, group 1 being the genes least tolerant of losing a copy. Missense variants: 845 observed, 906.75 expected, observed/expected ratio (o/e) 0.93, 90% interval 0.88 to 0.99. Synonymous variants: 276 observed, 296.73 expected, observed/expected ratio (o/e) 0.93, 90% interval 0.84 to 1.03.
Homologues: Orthologues: chimpanzee TTK (99% identical), macaque TTK (94% identical), pig TTK (88% identical), dog TTK (88% identical), rabbit TTK (86% identical), rat Ttk (78% identical), mouse Ttk (74% identical), tropical clawed frog ttk (53% identical), zebrafish ttk (44% identical). Paralogues in human: TLK2 (18% identical), TLK1 (18% identical).
Diseases named in the same sentence as TTK in open-access papers:
TTK is named in the same sentence as 103 diseases in open-access papers, as found by Europe PMC text mining. Sharing a sentence is not in itself a finding about the gene and the disease. The quoted sentences say what the papers report.
breast carcinoma (62 papers, 2012 to 2026). "In breast cancer, a higher threonine tyrosine kinase (TTK) expression is linked with effective homologous recombination-mediated repair and radiation sensitivity." (PMID 35957812, 2022). "TTK expression levels are associated with mesenchymal and proliferative phenotypes in breast cancer." (PMID 36726984, 2022). "High TTK protein kinase (TTK) expression in breast cancer is associated with efficient repair through homologous recombination and low radiation sensitivity." (PMID 33488669, 2020). "In the present study, the upregulated expression and corresponding diagnostic value of TTK in BRCA1/2-mutant breast cancer suggested that the role of TTK in this type of breast cancer is equally noteworthy." (PMID 31998560, 2020). "At present, many studies have found that high expression of dual specificity protein kinase (TTK), encoded by the TTK gene, is associated with the oncogenesis, progression and treatment resistance of breast cancer (especially TNBC)." (PMID 31998560, 2020). "According to the test set (GSE25055) and validation set (GSE426568), three hub genes (ASPM, CDC20, and TTK) were significantly associated with the prognosis of breast cancer patients." (PMID 31106147, 2019). "Among them, ASPM, CDC20, and TTK were negatively associated with relapse-free survival (RFS) of breast cancer patients using Kaplan Meier survival curves by log-rank test." (PMID 31106147, 2019). "We also explored the Kaplan Meier Plot resource and noted that MDM2 and SFRP1 are positively associated with relapse free survival in all breast cancer subtypes, while TTK is negatively correlated with overall survival of Luminal A patients." (PMID 25278993, 2014). "Increased TTK expression has high diagnostic efficacy for breast cancer screening." (PMID 36829176, 2023). "In addition, we have published that the overexpression of Nek2 or TTK mRNA is associated with poor overall- and relapse-free survival of breast cancer patients." (PMID 36494865, 2022). "A high TTK expression, moreover, is positively associated with higher grade aggressiveness and therapeutic resistance in breast cancer, implicating the TTK might be involved in cancer cell proliferation and poor patient survival rate." (PMID 33187219, 2020). "Importantly, this correlation was most relevant in basal-like breast cancers, whose loss of TTK expression inhibited their proliferation and sensitized them to DPH-mediated c-Abl activation." (PMID 28661474, 2017). "Finally, TTK is known to be upregulated in anaplastic thyroid carcinoma and associated with increased risk of breast cancer." (PMID 22539975, 2012). "In addition, diazoxide, a potassium channel opener, inhibits dual specificity tyrosine-phosphorylation-regulated kinase 1A (DYRK1A), an interleukin-1 receptor-associated kinase 1 (IRAK1), and threonine and tyrosine kinase (TTK) expression in breast cancer cell lines." (PMID 37370809, 2023). "This study investigates threonine and tyrosine kinase (TTK) expression in pre‐ and post‐neoadjuvant chemotherapy breast cancer patients." (PMID 39775836, 2025). "A five-gene SLE prognostic signature (RACGAP1, HMMR, TTK, TOP2A, and KIF15) effectively stratified breast cancer survival risk." (PMID 40567613, 2025). "Data suggests that high levels of TTK mRNA can protect breast cancer cells from aneuploidy, ensuring their proper chromosome segregation." (PMID 38886738, 2024). "Nowadays, five small molecule inhibitors of TTK are currently under clinical study for head and neck, endocrine, gastrointestinal, genitourinary, gynecologic, and breast cancers, as well as melanomas and sarcomas of the soft tissue and bone." (PMID 38658569, 2024). "We identified several DEGs involved in the cell cycle, including CDK1, CHEK1, CDC25C, BUB1, CDC20, and TTK, which not only are related to breast cancer patient survival but also have existing targeted drugs." (PMID 38166892, 2024).
breast carcinoma (continued). "Another strategy is to lower rates of chromosome instability by reducing high rates of centrosome amplification; this has been accomplished by the downregulation of TTK in Her2 + breast cancer cells." (PMID 38886738, 2024). "Given its role in the development of cancers, TTK has gained significant attention as a potential clinical therapy target, including breast cancer." (PMID 38886738, 2024). "Apart from these reports, Multiple breast cancer cell lines with a basal-like phenotype were more radiosensitive after TTK inhibition by B909." (PMID 36829176, 2023). "A TTK-targeting small drug (compound 13) dramatically suppressed breast cancer development in nude mice." (PMID 36829176, 2023). "In basal-like breast cancer, genetic and pharmacological inhibition of TTK was found to radiosensitize cancerous cells through inhibition of homologous recombination." (PMID 37770979, 2023). "Previous research has shown that TTK has an important tumor-promoting role in triggering EMT in breast cancer and bladder cancer." (PMID 36829176, 2023). "This analysis found more frequent upregulation of TTK in basal breast cancers (31.6% in TCGA and 32.2% in METABRIC) than in other subtypes." (PMID 36494865, 2022). "When we analyzed the gene expression of these kinases by subtype, TTK mRNA is more highly overexpressed in basal breast cancers from NHW and H/L patients, and Luminal A patients from H/L." (PMID 36494865, 2022). "TTK and TBK1 are significantly overexpressed in NHW women with basal breast cancers, and TTK in basal and Luminal A breast cancers from H/L women." (PMID 36494865, 2022). "The effect of TTK in the progression of breast cancer has been shown, while its role in liver cancer has received little attention." (PMID 36531219, 2022). "Inhibition of TTK activity sensitizes basal-like breast cancer to radiation therapy by destroying DNA repair efficiency." (PMID 35850753, 2022). "TTK/hMPS1 gene is known to play a role in centrosome duplication, and mitotic checkpoint signaling and is known to play a role in the progression of breast cancer." (PMID 36568153, 2022). "Nevertheless, our data revealed important associations between TTK expression and subtypes that associate with a poorer prognosis, including TNBC and Her2 + breast cancers." (PMID 36494865, 2022). "TTK is a dual-specificity protein kinase that abnormally expresses in various cancers, including breast cancer and prostate cancer." (PMID 35493518, 2022). "The expression levels of CCNA2, DEPDC1, and TTK (DOE-A) were significantly higher in BL/TNBCs than in luminal breast cancer cell lines." (PMID 34172056, 2021). "Evidence from pancreatic and breast cancers suggests that the mechanism of cell death following treatment with TTK inhibitors is induction of genomic instability." (PMID 34031527, 2021). "More future research about its mechanisms in TNBC will provide a theoretical basis for TTK inhibitor-targeted therapy in the field of breast cancer and TNBC." (PMID 31998560, 2020). "For example, upregulated CCNE1, TTK and EXO1 displayed good diagnostic efficacy for screening breast cancer and BRCA1/2-mutant breast cancer." (PMID 31998560, 2020). "CCNE1, NPBWR1, A2ML1, EXO1 and TTK displayed good prognostic/diagnostic value for breast cancer and BRCA1/2-mutant breast cancer." (PMID 31998560, 2020). "Overexpression of TTK correlate with poor prognosis in HER2-positive breast cancer and hepatocellular carcinoma." (PMID 31106147, 2019). "These genes include AURKB, BUB1, CHEK1, FOXM1, KIFC1, and TTK7, five of which, BUB1, CHEK1, FOXM1, KIFC1, and TTK, we have also identified and have functionally validated to have a selective requirement for cell growth in breast cancer cell models." (PMID 29535384, 2018). "In breast cancer, high TTK expression correlates with aggressive subtypes and therapeutic resistance." (PMID 30206215, 2018).
breast carcinoma (continued). "Altogether, this study highlights a novel role and signaling pathway for TTK in regulating EMT of TN breast cancer cells through TGF-β and KLF5 signaling, highlighting targetable signaling pathways for TTK inhibitors in aggressive breast cancer." (PMID 30206215, 2018). "CA causes mammary tumorigenesis in mice and correlates with high stage, grade, and poor relapse-free and overall survival of breast cancer patients, which suggests a role for TTK in mammary tumor development and progression." (PMID 30206215, 2018). "Genomic silencing of TTK in Her2+ breast cancer cells attenuates CA10, as does pharmacological inhibition (unpublished data)." (PMID 30206215, 2018). "In this regard, higher KLF5 expression associated with the TN status of breast cancer, and more specifically, KLF5 expression was higher in the basal A than basal B subtype of TNBC, which inversely correlated with TTK expression." (PMID 30206215, 2018). "To determine the significance of higher TTK expression in breast cancer, we analyzed TTK expression in three publically-available platforms." (PMID 30206215, 2018). "Analysis of breast cancer cell lines in the GOBO samples showed higher TTK expression correlated with Basal A and Basal B subtypes compared to the luminal subtype." (PMID 30206215, 2018). "Among 2091 breast cancer patients with both TTK expression and survival data available, higher TTK expression significantly correlated with decreased overall survival." (PMID 30206215, 2018). "To investigate other functional effects of inhibiting TTK with NMS-P715 in breast cancer, we treated cell lines with inhibitor and measured proliferation using the SRB assay." (PMID 30206215, 2018). "MCF10A mammary epithelial and DU-145 prostate cancer cell lines exhibit lower TTK, while higher TTK was detected in other breast cancer cell lines." (PMID 30206215, 2018). "In this study, we examined the correlations between TTK expression and clinical characteristics of breast cancer using publically-available databases, and confirmed the correlation between high levels of TTK expression with adverse features." (PMID 30206215, 2018). "Further analysis of tumors from different clinical subtypes of breast cancer in the GOBO database revealed higher TTK expression was most-significantly correlated with triple negative (TN) subtypes compared to all other subtypes." (PMID 30206215, 2018). "For example, high TTK expression correlates with poor prognosis in hepatocellular carcinoma and Her2-positive breast cancer, while low TTK expression correlates with poor patient outcome in TNBC." (PMID 28415765, 2017). "Previous studies show that TTK is overexpressed in breast cancer tissue and cells, particularly in the HER2-positive and TNBC subtypes." (PMID 27833085, 2016). "In the case of TTK, RNA level was negatively correlated with overall survival of luminal A breast cancer patients, showing statistical significance." (PMID 25278993, 2014).
breast carcinoma (continued). "Previous studies have revealed how modifying TTK expression levels affects cell viability, mitosis and tumor growth in vivo but none have addressed TTK’s functional roles involved with CA in breast cancer." (PMID 25278993, 2014). "Conversely, amongst upregulated genes in HCC1954 cells, knockdown of SGOL1 and TTK decreased CA in breast cancer cells, while BrdU incorporation was only altered by SGOL1 knockdown." (PMID 25278993, 2014). "In breast cancer, increased TTK mRNA levels have been noted across many cell lines, specifically Her2+ and triple negative subtypes and in tumor samples collected from patients with advanced disease." (PMID 25278993, 2014). "Based on this functional screen, we conclude that SGOL1 and TTK are important modulators of centrosome function in a breast cancer specific model." (PMID 25278993, 2014). "Further dissection of the mechanism for how TTK can drive CA and genomic instability in specific breast cancer subtypes will be a key to understanding the correlations between high TTK levels and more aggressive/drug resistant breast tumors." (PMID 25278993, 2014). "Together, these results highlight TTK as a potential therapeutic target for the TNBC subgroup of breast cancer." (PMID 23700430, 2013). "TTK mRNA expression was elevated in breast cancer tissues, predicting reduced survival." (PMID 39775836, 2025). "Notably, TTK protein expression in neoadjuvant chemotherapy‐treated breast cancer patients was up‐regulated post‐therapy and correlated with reduced survival, highlighting TTK as a breast cancer biomarker and possible therapeutic target." (PMID 39775836, 2025). "Moreover, TTK is known to be overexpressed in breast cancer cell lines, especially in HER2+ and TNBC, when compared to other subtypes and normal tissues." (PMID 38886738, 2024). "In addition, published studies had showed that the BID-overexpressing MDA-MB-468 breast cancer cells established in nude mice as xenografts were sensitive to the TTK inhibitors CFI-402,257 and BAY1217389." (PMID 37443114, 2023). "TTK induces EMT in breast cancer cells by upregulating miR-21 and decreasing miR-200c levels." (PMID 36829176, 2023). "A prognostic SLEscore consisting of five SLE-related genes (RACGAP1, HMMR, TTK, TOP2A, and KIF15) could distribute patients with breast cancer into the high- and low-risk groups according to survival rates with good predictive ability (p < 0.05)." (PMID 36726984, 2022). "From the correlation analysis, it can therefore be inferred that both CHAC2 and TTK may be potential candidate for future therapeutic targets in breast cancer." (PMID 36568153, 2022). "In the past, several reports have suggested an oncogenic role for TTK in breast cancer." (PMID 36568153, 2022). "Overexpression of TTK promotes tumor growth in prostate cancer, breast cancer and colon cancer." (PMID 34598710, 2021). "Furthermore, recent studies reported that genetic and pharmacological inhibition of TTK enhances radiosensitivity in basal-like breast cancer and liver cancer by inducing persistent DNA damage." (PMID 34876569, 2021). "In addition, TTK has been discovered to function as an oncogene in various cancers, and TTK inhibition has already been studied as a targeted therapy for breast cancer, glioblastoma, liver cancer and other tumors." (PMID 34876569, 2021). "Using the survival analysis, we found that CCNE1, NPBWR1, A2ML1 and TTK might act critical functions in the oncogenesis and progression of BRCA1/2-mutant breast cancer, reflected by their diagnostic efficacy for BRCA1/2 mutations and prognostic value as well." (PMID 31998560, 2020). "However, the level of TTK is high in many types of human malignancies, including glioblastoma, thyroid cancer, and breast cancer." (PMID 32530571, 2020). "TTK mRNA levels were elevated in lung, anaplasic thyroid and breast cancer." (PMID 31106147, 2019). "We then analyzed TTK expression in RNAseq data generated from breast cancers from TCGA." (PMID 30206215, 2018).